SESN2 (sestrin 2)
Description:
Functions as an intracellular leucine sensor that negatively regulates the mTORC1 signaling pathway through the GATOR complex. In absence of leucine, binds the GATOR subcomplex GATOR2 and prevents mTORC1 signaling. Binding of leucine to SESN2 disrupts its interaction with GATOR2 thereby activating the TORC1 signaling pathway. This stress-inducible metabolic regulator also plays a role in protection against oxidative and genotoxic stresses. May negatively regulate protein translation in response to endoplasmic reticulum stress, via mTORC1. May positively regulate the transcription by NFE2L2 of genes involved in the response to oxidative stress by facilitating the SQSTM1-mediated autophagic degradation of KEAP1. Moreover, may prevent the accumulation of reactive oxygen species (ROS) through the alkylhydroperoxide reductase activity born by the N-terminal domain of the protein. Was originally reported to contribute to oxidative stress resistance by reducing PRDX1. However, this could not be confirmed.
Synonyms: Hi95; SEST2; SES2; DKFZp761M0212
Tractability: Small molecule: a structure with a bound ligand is known. PROTAC: UniProt records ubiquitination sites on it; ubiquitination databases record sites on it.
Gene: Protein-coding gene on chromosome 1 (28,259,473 to 28,282,491, forward strand). Ensembl gene ENSG00000130766.
Subcellular location: Cytoplasm
Subcellular location (Human Protein Atlas): Cytosol
Pathways (Reactome):
Cellular responses to stimuli: Amino acids regulate mTORC1; KEAP1-NFE2L2 pathway
Gene Ontology:
Molecular function: L-leucine binding; peroxidase activity; PH domain binding; protein binding; protein sequestering activity; protein-containing complex binding; sulfiredoxin activity; oxidoreductase activity, acting on peroxide as acceptor; GDP-dissociation inhibitor activity
Biological process: activation of protein kinase activity; cellular oxidant detoxification; cellular response to amino acid starvation; cellular response to amino acid stimulus; cellular response to glucose starvation; cellular response to L-leucine; cellular response to leucine starvation; negative regulation of TORC1 signaling; negative regulation of translation in response to endoplasmic reticulum stress; positive regulation of macroautophagy; positive regulation of protein localization to nucleus; positive regulation of TORC1 signaling; protein localization to plasma membrane; reactive oxygen species metabolic process; regulation of protein phosphorylation; regulation of TORC1 signaling; TORC2 signaling; cellular response to oxidative stress; negative regulation of cell growth; regulation of response to reactive oxygen species
Cellular component: Atg1/ULK1 kinase complex; cytoplasm; GATOR2 complex; lysosomal membrane; cytosol; nucleotide-activated protein kinase complex; TORC2 complex; nucleus
Genetic constraint (gnomAD): Loss-of-function variants: 35 observed, 46.78 expected, observed/expected ratio (o/e) 0.75, 90% interval 0.57 to 0.99. The upper end of that interval is the gene's LOEUF score, 0.99, which puts it in group 4 of 6, group 1 being the genes least tolerant of losing a copy. Missense variants: 467 observed, 600.35 expected, observed/expected ratio (o/e) 0.78, 90% interval 0.72 to 0.84. Synonymous variants: 251 observed, 252.31 expected, observed/expected ratio (o/e) 0.99, 90% interval 0.9 to 1.1.
Homologues: Orthologues: chimpanzee SESN2 (99% identical), macaque SESN2 (99% identical), guinea pig SESN2 (95% identical), dog SESN2 (95% identical), pig SESN2 (94% identical), rabbit SESN2 (93% identical), rat Sesn2 (92% identical), mouse Sesn2 (91% identical), zebrafish sesn2 (55% identical), Drosophila melanogaster Sesn (42% identical), Caenorhabditis elegans sesn-1 (25% identical). Paralogues in human: SESN1 (57% identical), SESN3 (56% identical).
Diseases named in the same sentence as SESN2 in open-access papers:
SESN2 is named in the same sentence as 159 diseases in open-access papers, as found by Europe PMC text mining. Sharing a sentence is not in itself a finding about the gene and the disease. The quoted sentences say what the papers report.
colon carcinoma (26 papers, 2012 to 2025). "Loss of SESN2 promoted colon cancer growth and reduced susceptibility to chemotherapeutic treatments, as evidenced by dramatically increased tumor size and burden." (PMID 31867002, 2019). "However, the extent of copy number loss was very small (~10%), suggesting that transcriptional downregulation, rather than the loss of genomic information, is the major mechanism of SESN2 inhibition during colon cancer progression." (PMID 26913956, 2016). "Thus, Sesn2-/- mice were subjected to an established protocol of colitis-associated colon cancer induction; in this model, colon carcinogenesis is initiated by azoxymethane (AOM) administration and promoted by repeated colon injury induced by 2.5% DSS." (PMID 26913956, 2016). "Several studies confirmed that SESN2 promoted apoptosis of various cancer cell types, including lung adenocarcinoma, colon cancer, human head and neck cancer, and others." (PMID 40775338, 2025). "Studies have portrayed SESN2 as a central regulator of mTORC1 signaling, inhibiting colon cancer development." (PMID 39759146, 2024). "Their experiments revealed that experimentally overexpressed SESN2 inhibits HIF-1α accumulation in colon cancer cell lines HCT116 and HT29 exposed to hypoxic condition and prevents cancer cell metastasis." (PMID 37284849, 2023). "In one instance low sestrin 2 expression appears to be beneficial for colitis, while elevated expression of sestrin 2 appears to be beneficial for colon cancer." (PMID 33673488, 2021). "This study suggested that sestrin 2 has a promotive effect on colon cancer during high iron conditions." (PMID 34784907, 2021). "Similar to our findings RE induced apoptosis in colon cancer cells through a nuclear factor erythroid 2-related factor 2 (Nrf2)/sestrin-2 pathway, which required phosphorylation/activation of ERK." (PMID 35054445, 2021). "Cystine indeed robustly promotes colon cancer cell growth in vitro and in immunodeficient mice, predominately by inhibiting SESN2 transcription via the GCN2-ATF4 axis, resulting in mTORC1 activation." (PMID 34045438, 2021). "Several studies indicated that SESN2 levels were significantly decreased in colon adenocarcinoma tissues, and low expression of SESN2 promoted colon tumour growth." (PMID 33942488, 2021). "It was reported that SESN2 acted as a potential suppressor in the colon during intestinal inflammation and colon cancer progression and contributed to maintaining intestinal homeostasis." (PMID 31867002, 2019). "High expression of SESN2 was found to induce apoptosis through the AMPK/p38 signaling pathway in colon cancer cells." (PMID 28118855, 2017). "These immunohistochemical observations were also confirmed by immunoblotting experiments; S6 and 4E-BP phosphorylation was prominently increased in colon tumors of Sesn2-/- mice, compared to those of WT mice." (PMID 26913956, 2016). "SESN2 genome copy is also significantly reduced in colon cancer, and decreases further as the colon cancer progresses." (PMID 26913956, 2016). "This modification enabled both WT and Sesn2-/- groups to survive through three inflammatory and recovery phases, and develop macroscopically visible colon tumors at 100 days after AOM injection." (PMID 26913956, 2016).
colon carcinoma (continued). "Detailed studies of inflammation-associated colon cancer showed that mice knockout of Sesn2 did not influence tumour initiation but dramatically increased the size of the tumours." (PMID 40361504, 2025). "Likewise, SESN2 is found downregulated in colon cancer, where STAT3 is often hyperactivated and contributes to carcinogenesis." (PMID 39985075, 2025). "However, in colon cancer and endometrial cancer cell lines, the increased expression of Sesn2 can inhibit cancer by inhibiting mTOR." (PMID 41614860, 2025). "In contrast to the previous study, 5-FU did not induce the ROS production in colon cancer cell lines; thus, a different molecular mechanism was implicated in SESN2 upregulaion." (PMID 37284849, 2023). "Additionally, drugs like 5-Fluorouracil or quercetin induced SESN2 expression as well, but a SESN2 knockdown attenuated drug-mediated effects in colon cancer cells." (PMID 36611970, 2022). "Hemin (Fe3+ heme) induced the expression of sestrin 2 by activating ROS and nuclear factor (erythroid-derived 2)-like 2, and, together with hemin, sestrin 2 overexpression protected colon cancer cells from death including HCT116 and RKO cells and promoted MC38 tumor growth both in vitro and in vivo." (PMID 34784907, 2021). "In addition, high expression of SESN2 decreased murine colon tumour cell growth both in vitro and in vivo." (PMID 33942488, 2021). "Moreover, SESN2 was strongly decreased in colon adenocarcinoma tissues, and its expression was downregulated in correlation with the progression of colon cancer." (PMID 31867002, 2019). "Similarly, HCT116 colon cancer xenografted mice showed increased Nrf2 and Sestrin-2 expression which are indicative of endoplasmic reticular stress and can lead to enhanced apoptosis." (PMID 27869665, 2016). "Therefore, we analyzed mTORC1 downstream target proteins in colon cancer and normal colon tissues from WT and Sesn2-/- mice through immunohistochemistry." (PMID 26913956, 2016). "Moreover, they treated SESN2-silenced RKO cells with two representative chemotherapeutic agents, 5-fluorouracil (5-FU) and irinotecan (CPT-11), to asses if SESN2 may be important for the responsiveness of colon cancer cells to chemotherapeutic treatments." (PMID 37284849, 2023). "However, given the strong correlation between SESN2 expression and colon cancer tumorigenesis in humans, we reasoned that endogenous Sestrin2 may play a role in attenuating tumor development and progression." (PMID 26913956, 2016). "SESN2 was recently reported to be an inhibitor of the WNT-β-Catenin signaling pathway, the major regulator of cell stemness and proliferation in colon carcinoma cells." (PMID 39985075, 2025). "The treatment of colon cancer cells (HCT116 and HT-29) with quercetin also increases sestrin-2 expression and induces apoptosis." (PMID 38396629, 2024). "In a study of the impact of Sestrins in colon cancer, mice knockouts of Sesn2 did not develop more tumours." (PMID 40361504, 2025). "Indeed, cystine inhibited GCN2 phosphorylation and downregulated nuclear ATF4 protein levels, which decreased transcription of SESN2 and ultimately activated mTORC1 in both HCT116 and RKO colon cancer cell lines." (PMID 34045438, 2021).
colon carcinoma (continued). "Interestingly, quercetin reduces mitochondrial membrane potential, sustains intracellular ROS production and increases SESN2 expression, favoring apoptosis and cell death in HCT116 and HT-29 colon cancer cells." (PMID 31546746, 2019). "However, numerous other studies indicated lower expression of SESN2 in several cancers, including hepatocellular carcinoma, non-small cell lung cancer, bladder cancer, and colon cancer tissues than that in non-cancerous tissues." (PMID 32899752, 2020). "The analysis of two-year-old WT and Sesn2-/- mice (n=6 each) did not reveal any noticeable colon tumors, suggesting that Sesn2 may not be a classical tumor suppressor gene whose homozygous deletion is sufficient to induce spontaneous cancer development." (PMID 26913956, 2016). "The authors clearly demonstrated that colon cancer HCT116 and HT29 cell lines treated with 5-FU expressed a higher level of SESN2 and increased transcripts of SESN1, but not of SESN3 protein." (PMID 37284849, 2023).
Sepsis (24 papers, 2018 to 2025). Sepsis is defined as life-threatening organ dysfunction caused by a dysregulated host response to infection. "Previous investigations have revealed that Sesn2-deficient mice exhibited impaired mitophagy, resulting in heightened inflammasome activation, and increased mortality in sepsis models." (PMID 38348451, 2024). "Taken together, these data indicated that SESN2 deficiency aggravated the inflammatory storm in the early stage of sepsis." (PMID 34741186, 2021). "We further focused on the response of ERS in DCs to explore the precise mechanisms underlying cytoprotective actions of SESN2 against apoptosis induced by HMGB1 or during sepsis." (PMID 32071292, 2020). "Therefore, mice deficient in SESN2 display impaired mitophagy in two distinct sepsis models, leading to hyperactivation of the inflammasome and ultimately elevated mortality." (PMID 38020710, 2023). "Thus, the current study was purposed to explore a regulatory effect of Sesn2 on ferroptosis of DCs and identify the underlying signaling pathway in the setting of sepsis." (PMID 34482365, 2021). "Moreover, SESN2 deficiency strongly aggravated ERS responses in DCs during sepsis, as evidenced by upregulation of GRP78 and ATF4 in CLP mice." (PMID 32071292, 2020). "Meanwhile, deficiency of SESN2 showed defective mitophagy, caspase-1 hyperactivation, and increased secretion of IL-1β and IL-18, which ultimately increased the mortality in murine sepsis." (PMID 31867002, 2019). "A report illustrated that SESN2 shields dendritic cells from sepsis-induced ferroptosis through the ATF4-CHOP-CHAC1 signaling pathway." (PMID 39037665, 2025). "Studies have indicated that SESN2 can suppress ferroptosis of DCs in sepsis by downregulating the Atf4/Chop/Chac1 signaling pathway (Li J.-Y." (PMID 39944356, 2024). "Further research demonstrated that SESN2 protected DCs against sepsis-induced ferroptosis through an activating transcription factor 4 (ATF4)–C/EBP homologous protein (CHOP)–cation transport regulator homolog 1 (CHAC1)-dependent manner." (PMID 38816685, 2024). "In conclusion, SESN2 contributes to immune response modulation and oxidative stress pathways central to sepsis pathophysiology." (PMID 38348451, 2024). "While SESN2 research has primarily focused on cancer and metabolic diseases, emerging evidence suggests its relevance to sepsis." (PMID 38348451, 2024). "In sepsis models, SESN2 levels in blood monocytes negatively correlate with serum IL-1β and IL-18 levels and disease progression." (PMID 36841824, 2023). "SESN2 also reduces gasdermin D (GSDMD)-dependent pyroptosis of splenic DCs in the context of sepsis via inhibiting PERK-ATF4-CHOP signaling-triggered NLRP3/ASC pyroptosome formation and Caspase-1 activation." (PMID 36841824, 2023). "Our previous studies demonstrated that the PERK–ATF4–CHOP signaling pathway was critical for SESN2 alleviating the apoptosis, pyroptosis and ferroptosis of dendritic cells in sepsis." (PMID 36873287, 2023). "SESN2 can play an antioxidant role in sepsis, downregulating the ATF4-CHOP-CHAC1 signaling pathway and inhibiting ferroptosis in dendritic cells." (PMID 36685932, 2022). "Sesn2 inhibits the ferroptosis of DCs in sepsis by down-regulating the ATF4-CHOP-CHAC1 signaling pathway and exerts an antioxidant effect." (PMID 35619718, 2022). "It was reported that Sesn2 served as a protective gene against sepsis-induced ferroptosis and iron overload and ferroptosis-induced liver injury." (PMID 36238640, 2022). "First, the modulatory effect of Sesn2 on the host immune response of DCs warrant further study in the setting of sepsis." (PMID 34482365, 2021). "The protective impact of SESN2 in regulating NLRP3 inflammasome-dependent pyroptosis is consistent with a recent report showing that SESN2 protects the host from sepsis by suppressing prolonged activation of the NLRP3 inflammasome." (PMID 34741186, 2021).